IL6 (interleukin 6)
Diseases named in the same sentence as IL6 in open-access papers (continued):
Sharing a sentence is not in itself a finding about the gene and the disease.
bacterial infection (continued). "As well-known inflammatory cytokines or chemokines, IL-1β, IL-8, IL-6, TNF-α and TLR4 are involved in various types of inflammatory responses, and play key roles in the inflammatory process during bacterial infection of bovine mammary glands." (PMID 36233122, 2022). "Increased IL-6, IL-8, IL-10 and TNF-α concentrations have been reported following surgical procedures and in the early stages of bacterial infections both in adults and children." (PMID 36154663, 2022). "It has also been reported that PCT was of better specificity and sensitivity in diagnosing bacterial infection when compared with either white blood cell (WBC), C-reactive protein (CRP), or interleukin-6 (IL-6)." (PMID 35722120, 2022). "For patients with EBV infection, besides IL-6 and IL-10, IFN-γ usually elevated, which is different from bacterial infection." (PMID 35391735, 2022). "The extract can affect the COX-2 pathway by affecting the release levels of TNF-α, IL-6, and PGE2, which are key mediators released by macrophages during bacterial infection, so as to achieve the purpose of anti-inflammatory." (PMID 36234947, 2022). "Because the epithelium is the first line of defense against bacterial infection and we found that PFWE inhibited the expression of IL-6 and CCL2/MCP-1 genes in the LPS-challenged lungs in mice, we further investigated the potential mechanisms." (PMID 35815275, 2022). "IL-17 is induced during bacterial infection, and in turn induces the production of inflammatory cytokines including IL-1, GM-CSF, TNF-α, and IL-6, and chemokines such as MCP-1, MCP-3, and MIP-3A." (PMID 36386225, 2022). "The IL-6, IL-10 and TNF cytokines are produced by activated macrophage cells as a positive response of inflammatory reactions in the process of bacterial infection." (PMID 35369436, 2022). "Second trimester placental explants (16–20 weeks, n = 5/group) were treated with lipopolysaccharide (LPS, to mimic bacterial infection) and ACE2, CCL2, IL-6/8 and TNFα mRNA was assessed." (PMID 34359894, 2021). "IL-6 is a primary determinant of hepatic production of CRP and plays a key role in acute-phase inflammatory responses to for example viral or bacterial infections." (PMID 33948158, 2021). "Here, C. perfringens challenged groups showed a numerical up‐regulation in the expression of IL6 and IL8 due to the inflammation induced by the bacterial infection." (PMID 33720539, 2021). "LPS endotoxins are widely used as experimental models of systemic bacterial infection and trigger inflammatory factors such as TNF-α, IL-1β and IL-6." (PMID 33557833, 2021). "Upon the inclusion of these 10 indicators in multivariate analysis, the results showed that WBC, NEUT, CRP, PCT, IL-6, and IFN-γ were independent predictors for bacterial infections in SLE." (PMID 33732661, 2021). "It was previously shown that in vitro knockdown of NLRP12 up-regulated IL-6 and TNF-α expression in bacterial infections, such as salmonella and Klebsiella pneumonia infection." (PMID 34956178, 2021). "In the bacterial infection model (LPS), SNV significantly reduced IL1β expression, while VIP increased IL6 expression." (PMID 34025407, 2021). "Among them, pro-inflammatory cytokines (IL-6, TNF-α) and chemokines (MCP-1, MIP-2) are representative mediators released in response to bacterial infection." (PMID 32153410, 2020). "Most of the studies found that PCT was dominant in differentiating viral and bacterial infections compared to hs-CRP and IL-6." (PMID 32462018, 2020). "Bacterial infection first activates the host’s innate immune response, producing a series of inflammatory cytokines, such as TNF-α, IL-6, and IL-10." (PMID 32913259, 2020). "Consistent with the results in mice, we found that knockout or knockdown of MARCH2 in immune cells reduced viral replication or bacterial growth, and led to higher production of IL‐6, IL‐12, and IFN‐β production upon virus or bacterial infection." (PMID 32935379, 2020).
bacterial infection (continued). "Whereas LPS, widely used to mimic bacterial infections in vitro, evoked distinct pro-inflammatory responses in HBMEC, expressed by mRNA and protein increases for CXCL5, IL-1α, IL-1β, IL-6, IL-8, MCP-1, MCP-3, and TNF-α, Ureaplasma spp." (PMID 31336668, 2019). "The host-protein signature yielded significantly higher total accuracy for differentiating between viral and bacterial infections than PCT, CRP, HNL, IL-6, WBC, ANC (all p values lower than 0.02), while assigning 10.2% of patients equivocal results." (PMID 29700762, 2018). "Bone-resorbing cytokines such as IL-1β, TNF-α, IL-6, and RANKL are produced in reaction to bacterial infections and induce ABL." (PMID 29670725, 2018). "The detection of inflammatory biomarkers such as IL-6 and C-reactive protein (CRP) in urine hold significance in the preliminary detection of chronic diseases as well as bacterial infections." (PMID 29796304, 2018). "Key inflammatory cytokines released during the early response to bacterial infection are: tumour necrosis factor (TNF), interleukin 1 (IL-1) and interleukin 6 (IL-6)." (PMID 30263032, 2018). "The combination of IL-6 and CRP plasma biomarkers can even be used to predict serious bacterial infections in young febrile infants." (PMID 27977798, 2016). "Bacterial infection alone led to a transient increase in IFN-γ at 6 hpi and IL-6 at 6 hpi and 18 hpi, which hardly reached the elevated IFN-γ and IL-6 levels detected in the IAV-infected group at all time points analyzed." (PMID 27872472, 2016). "Interleukin 6 (IL-6), acting via the IL-6 receptor (IL6R) and signal transducer and activator of transcription-3 (STAT3), limits neutrophil recruitment once bacterial infections are resolved." (PMID 26813342, 2016). "It has been known that IL-6 and TNF-α secretion by macrophages upon bacterial infection in turn enhances their phagocytic capacity, thus promoting the clearance of pathogens." (PMID 26439699, 2015). "VDR activation suppresses hepatic Il6 expression and plasma IL-6 levels increased by BDL, and bacterial infection increases serum IL-6 levels to a greater extent in VDR-null mice." (PMID 23240054, 2012). "PCT is produced ubiquitously in response to endotoxin or mediators released in response to bacterial infections (that is, interleukin (IL)-1β, tumor necrosis factor (TNF)-α, and IL-6) and strongly correlates with extent and severity of bacterial infections." (PMID 21936959, 2011). "Notably, RIG-I knockdown significantly reduced IL-6 and IFN-β production across all cell types, indicating that RIG-I plays a role in stimulating both inflammatory and type I IFN responses during bacterial infection." (PMID 41341589, 2025). "Notably, in vivo bacterial infection model, QRs increased the proportion of M2 macrophages, stimulated endothelial cell proliferation, reduced the secretion of TNF-α and IL-6 in the tissue microenvironment, and accelerated the rapid healing of wound tissue." (PMID 40612279, 2025). "Notably, a significant correlation has been observed between bacterial infection in DKA and the biomarkers C-reactive protein (CRP) and interleukin-6 (IL-6)." (PMID 39946377, 2025). "Clinically, CRP, TNF-α, and IL-6 are utilized to assess inflammatory responses, with CRP produced by hepatocytes in response to inflammation and TNF-α and IL-6 playing roles in immune cell activation and serving as key indicators of bacterial infection." (PMID 40005662, 2025). "The activation of an innate immune system (involving monocytes and macrophages) by viral/bacterial infections or tissue damage results in the secretion of inflammatory mediators, such as nitric oxide (NO), tumor necrosis factor-α (TNF-α), and interleukin-6 (IL-6)." (PMID 40723879, 2025). "Bacterial infection models showed higher levels of LTA+/LPS+ EVs in infected groups compared to controls, correlating with increased inflammatory markers like interlinleukin‐6 ( IL‐6) and c‐reactive protein (CRP)." (PMID 40903799, 2025).
bacterial infection (continued). "In rat serum, IL-1β, IL-6, and TNF-α levels were significantly elevated, and increased internal bacterial infection and toxins were detected, implicating internal bacterial infection and toxin release as major factors in increased mortality after RCI." (PMID 41226494, 2025). "IL-6 is elevated in both conditions, while PCT is more specific to bacterial infection." (PMID 41347097, 2025). "Anti-IL-6 neutralizing antibodies have been previously found in four patients with severe staphylococcal and bacterial infections and no increase in serum CRP." (PMID 40977713, 2025). "Together, TBC1D9 enhances IL-6 expression in epithelial cells during cytosolic DNA sensing and various bacterial infections, sustaining homeostatic NF-κB activity but not stimulus-induced activation." (PMID 41306588, 2025). "This activation triggers intracellular signaling pathways, culminating in the synthesis and release of proinflammatory cytokines such as interleukins (e.g., IL-1 and IL-6) and tumor necrosis factor (TNF), which play crucial roles in the immune response against bacterial infections." (PMID 38826807, 2024). "Moreover, SP supplementation alone or mixed with Bacillus licheniformis enhanced the transcriptional levels of Lysozyme, Il-6, Il-1β, Tgf, and TNF-α, which in turn increased the goldfish resistance to bacterial infection and lowered its mortality rate." (PMID 39453066, 2024). "Cytokines such as IL‐1β, IL‐2, IL‐5, IL‐6, IL‐8, IL‐12p70, IL‐17, and TNF‐α may be involved in the progression of COVID‐19 combined with bacterial infection." (PMID 39692539, 2024). "Platelet depletion did not significantly affect systemic IL-1β, TNFα, and IL-6 levels in mice, consistent with previous findings in LPS challenge and bacterial infection." (PMID 38977927, 2024). "In the aPDI groups, the expression of IL-1β was still observed, but IL-6 was almost not expressed, indicating that the bacterial infection had been controlled after aPDI." (PMID 38970013, 2024). "Elevated concentrations of IL-1β, IL-6, and TNF-α in children may be correlated with OM; in particular, IL-6, a marker of a bacterial infection, can induce C-reactive protein (CRP) production and appears to play a vital role in inflammation in OM." (PMID 36911197, 2023). "Accumulating evidence has shown that levels of inflammatory biomarkers, including WBC, CRP, NE%, ESR, PCT, IL-6, and IL-10, were significantly higher in patients with bacterial infection than those with non-bacterial infection." (PMID 37986183, 2023). "For non-NPMODS patients, “IL-6 IL-10 ratio” after G- bacterial infection was statistically higher (p < 0.05) with a non-overlapping confidence interval (4.295, 95% CI 3.16–8.27) compared to G+ bacterial infection (2.470, 95% CI 1.37–3.18)." (PMID 36544765, 2022). "Of the 39 cases with low IL-6, 69.2% was confirmed as non-bacterial infection, while 72.7% of cases with high IL-6 were confirmed as bacterial infection." (PMID 35391735, 2022). "When bacterial infections occur, the circulation levels of PCT increase, mainly due to the presence of bacterial endotoxins and exotoxins, as well as inflammatory cytokines, such as TNF, IL-2, and IL-6." (PMID 36553115, 2022). "In the NPMODS subgroup, however, only IL-10 exhibited statistical differences between G+ and G- bacterial infection (p < 0.005), while IL-6 was significantly elevated regardless of bacterial Gram type." (PMID 36544765, 2022). "We then tested the performance of CRP, IL-6, and IL-10 to predict bacterial infection; the AUCs of CRP, IL-6, and IL-10 were 0.614 (95% CI, 0.531–0.697), 0.703 (95% CI, 0.626–0.780), and 0.657 (95% CI, 0.577–0.737), indicating IL-6 was the most powerful biomarker to predict bacterial infection." (PMID 35391735, 2022). "The AUCs calculated from the ROC curves were 0.7350 (95% CI: 0.6118‐0.8582) for G‐CSF and 0.6431 (95% CI: 0.4938‐0.7888) for IL‐6, whereas other four cytokines failed to differentiate the two types of bacterial infections." (PMID 34725873, 2021).
bacterial infection (continued). "PCT, which is a marker of bacterial infection produced by a pathway independent of IL-6, has been proposed as a preferred surrogate marker of bacterial infection during TCZ treatment." (PMID 34533616, 2021). "Combining WBC, NEUT, CRP, PCT, IL-6, and IFN-γ in a bioscore system may result in faster prediction of bacterial infections in SLE and may guide toward a more appropriate, timely treatment for SLE." (PMID 33732661, 2021). "The half-life of IL-6 in mice is between 8 and 12 h, suggesting that the IL-6 response to the burn occurred rapidly but did not persist in the absence of a secondary insult, such as a superimposed bacterial infection." (PMID 34152806, 2021). "Relative gene expression and protein level of pro-inflammatory cytokines (TNF-α, IL-6, IL-8), IL-10, TLR-2 and SERT were measured in fully differentiated Caco-2 monolayers following 24 h of bacterial infection in the presence of different levels of 5-HT (0, 100, 250, 500 ng/mL)." (PMID 34799637, 2021). "In addition, MC degranulated and produced ROS, TNF-α, IL-1β, IL-6, IL-13 and MCP-1 in response to bacterial infection." (PMID 34194428, 2021). "Procalcitonin, which is a marker of bacterial infections and is produced by pathways independent of IL-6, have been proposed a as preferred surrogate marker of bacterial infection during TCZ treatment." (PMID 33804790, 2021). "Different tools have been evaluated to establish an early diagnosis of bacterial infection through the use of inflammatory response biomarkers such us C-reactive protein (CRP), procalcitonin (PCT), interleukin 6 (IL-6) and more recently, mid-regional pro-adrenomedullin (MR-proADM)." (PMID 34828740, 2021). "Combining WBC, NEUT, CRP, PCT, IL-6, and IFN-γ in a bioscore system may result in a faster prediction of bacterial infections in SLE and may guide toward a more appropriate, timely treatment for SLE." (PMID 33732661, 2021). "In contrast, the specific blockade of the IL-6/sIL-6Rα trans-signaling pathway, which is achieved by treatment with sgp130Fc, still allows non-blocked IL-6 to support productive immune responses in defense against bacterial infections." (PMID 33334075, 2020). "This suggests that, in the context of phage therapy, the inflammation measured as the expression of IL-6 of hCMEC cultures is mainly induced by the influx of bacterial endotoxins released by phage lysis rather than the bacterial infection itself." (PMID 32483257, 2020). "This stimulation activates the transcription factor NF-кB, a protein complex that is crucial for the production of pro-inflammatory cytokines such as IL-1, IL-6 and TNF-α, which are important for the response to bacterial infections and the induction of sickness behaviour." (PMID 32717860, 2020). "The most clearly differentiating biomarker between control patient samples and either bacterial infection or non-bacterial inflammation was IL-6." (PMID 33409494, 2020). "During bacterial infections, SLE patients usually present with an adequate CRP-response which may be due to the massive increase of IL-6 that overrides the inhibitory effect of type I IFNs and/or genetic variants of CRP." (PMID 33584722, 2020). "Elevated serum IL-6 and TNF-α are capable of predicting the severity of bacterial infection." (PMID 31938070, 2020). "Six single-arm studies reported secondary bacterial infections, with an overall rate of 14.35%, which was also remarkably lower than that of the SOC group (14.35 vs. 17.36%, p < 0.0001) and the anti-IL-6 signaling group (14.35 vs. 25.98%, p < 0.0001) in the meta-analysis." (PMID 33384605, 2020). "Of note, recent animal studies demonstrated that chronic hypoxemia with absent bacterial infection resulted in mildly growth restricted offspring and increased IL-6 and TNF-α in fetal sera." (PMID 31743377, 2019). "Patients with severe bacterial infection without elevation of CRP should be examined for the presence of anti-IL6 autoantibodies." (PMID 31781117, 2019).
bacterial infection (continued). "Moreover, the upregulated levels of proinflammatory cytokines IL-1β, IL-6 and TNFα in the serum of mice infected by SL1344 manifested their stronger resistance to bacterial infection, which implied that the SL1344 had posed higher virulence to hosts." (PMID 30898022, 2019). "Neutralizing anti-IL-6 antibodies have been described in recurrent episodes of bacterial infections without an increase in C-reactive protein (CRP) level, consistent with impaired IL-6 mediated synthesis of this acute-phase reactant by the liver." (PMID 31892200, 2019). "Elevated PCT is commonly associated (although not strongly) with bacterial infections; it may be increased either directly by bacterial endotoxins and lipopolysaccharides or indirectly by inflammatory mediators (such as tumour necrosis factor-alpha, interleukin-6, interleukin-1)." (PMID 30999808, 2019). "Macrophages activated by inflammatory stimuli such as LPS in bacterial infections secrete pro-inflammatory cytokines such as TNF-α, IL-1, IL-6 and other soluble mediators such as nitric oxide (NO), which play a crucial role in induction and progression of the inflammatory response." (PMID 29141025, 2017). "To investigate whether Mincle suppresses bacterial infection, we examined the production of TNF-α and IL-6 by BM neutrophils infected with live E. coli." (PMID 28112221, 2017). "Compared with patients with other bacterial infections, those with β-haemolytic streptococcal infection had higher levels of IL-6, IL-10 and TNF-α but not a higher IL-1β level." (PMID 28176831, 2017). "In the presence of bacterial infection for example, inflammation is normally triggered, and the subsequent release of MIF allows for prolonged inflammation through the release of other pro-inflammatory cytokines like TNF-α, IL-1β, IL-6, IL-8, IL-2, and IFN-γ." (PMID 26741693, 2016). "As a consequence, plasma TNF-α and IL-6 levels are higher in cirrhotic patients with bacterial infection than in non-cirrhotic patients." (PMID 23601847, 2013). "Regarding IL-6 and TNF-α serum levels, the data of the present study are in agreement with previous studies, which demonstrated important limitations of these two inflammatory cytokines as biomarkers of bacterial infection." (PMID 23690657, 2013). "Elevated IL-1β, IL-6, and IL-8 could be used to differentiate patients with suspicious IC/BPS and inflammatory reactions after bacterial infection." (PMID 24146927, 2013). "We found significant differences in IL-6, IL-10 and LBP concentrations between patients with unknown pathogens and those with typical bacterial infections." (PMID 22348735, 2012). "Bacterial infection (LPS) or metabolic alterations (palmitate) have distinct effects on IL-6 expression in hBSMC, (i) short term LPS induced autocrine JAK/STAT signaling and (ii) long-term endocrine regulation of IL-6 by palmitate." (PMID 20526368, 2010). "Interestingly, mice that survive bacterial infections produce less TNF-α and IL-6 cytokines, the important mediators of fatal septic shock." (PMID 17059608, 2006). "The inability to detect other cytokines, like IL-1α or IL-6, that are known to be produced by keratinocytes in response to bacterial infection may be attributable to several, not further investigated factors." (PMID 40387366, 2025). "However, no previous study has investigated the relationship between IL-6 and liver injury induced by bacterial infection in fish." (PMID 38139043, 2023). "All types and concentrations of GSOP treatments could decrease IL-6 levels, while in the case of IL-8, GSOPs at a 50 μg/mL concentration were not effective when applied before or after bacterial infection." (PMID 35052987, 2022). "Finally, drug-loaded hydrogels were demonstrated to have remarkable antibacterial and anti-inflammatory activities by their significant (p < 0.05) reduction in both harmful S. aureus bacterial infection and the levels of painful TNF-α, IL-6, and IL-8 pro-inflammatory cytokines." (PMID 35448124, 2022).